CYP2E1 (cytochrome P450 family 2 subfamily E member 1)
Diseases named in the same sentence as CYP2E1 in open-access papers (continued):
Sharing a sentence is not in itself a finding about the gene and the disease.
Hepatic steatosis (continued). "Taken together, these results suggest that the increased CYP2E1 activity is not sufficient to cause and the onset of liver steatosis or mitochondrial proteome defects." (PMID 22187660, 2012). "The importance of induction of CYP4A genes in hepatic steatosis and steatohepatitis was revealed in Cyp2e1-null mice that developed severe steatohepatitis with a pronounced increase in CYP4A10 and CYP4A14 associated with increased accumulation of lipid peroxides." (PMID 20300478, 2009). "Finally, we discuss the function of CYP4A11 and CYP2E1 saturated fatty acid metabolites serving as anaplertoic metabolites for fatty acid and cholesterol synthesis leading to increased lipid droplet formation in hepatic steatosis." (PMID 40452921, 2024). "Previous studies using CYP2E1-overexpressed HepG2 cells or knock-in mice demonstrated that oxidative stress is increased, lipid peroxidation and apoptosis occur in cells, and elevated hepatic steatosis and liver injury occur in hepatic tissues after the administration of alcohol." (PMID 38398866, 2024). "However, the role of 19-HETE produced by CYP2E1 P450 has not been explored in association with alcoholic-associated or metabolic-associated fatty liver disease." (PMID 40452921, 2024). "In addition, many natural products, such as indole-3-carbinol, diallyl sulfide, phenethyl isothiocyanate, resveratrol, berberine, melatonin, lycopene, ellagic acid, silibinin, silymarin, gallic acid, walnut phytochemicals, etc., can suppress CYP2E1 activity and thus, fatty liver disease." (PMID 34573017, 2021). "LGS significantly improved liver steatosis, enhanced activities of alcohol metabolizing enzymes (ALDH and ADH), and reduced the CYP2E1 activity." (PMID 39734674, 2024). "To further investigate the rationale for the role of USP14 in promoting hepatic steatosis, we assessed the effect of USP14 on CYP2E1 both in vivo and in vitro." (PMID 37633951, 2023). "Changes in the cytochrome P450 protein family (CYP2E1 and CYP4A) reflect hepatic lipid dysmetabolism and can also contribute to the early phase of ovariectomy-induced hepatic steatosis." (PMID 33926097, 2021). "Increased CYP2E1 (p ˂ 0.05) and decreased CYP4A (p ˂ 0.001) after ovariectomy reduced fatty acid oxidation and induced hepatic steatosis." (PMID 33926097, 2021). "Alcohol exposure increases the activity of cytochrome P450 2E1 (CYP2E1), a major contributor to reactive oxygen species (ROS) generation, which is also involved in the development of fatty liver." (PMID 31906014, 2019). "Our results were also supported by indirect colorimetric measurements for the first time that Cyp2e1-null mice-FF exhibited an overall higher TEE, FO and AA, all of which can facilitate the development of hepatic steatosis." (PMID 28051126, 2017). "Additionally, we studied the differential energy expenditure and ambulatory activities in both western FF-fed mouse strains by indirect calorimetry which may explain the different rates of body weight gain and hepatic steatosis in WT-FF and Cyp2e1-null-FF groups." (PMID 28051126, 2017). "The non-competitive CYP2E1 inhibitor, clomethiazole, attenuates acute ethanol-induced hepatic steatosis by suppressing oxidative stress, an adiponectin decline, and an activation of autophagy." (PMID 37629519, 2023). "Activated cytochrome P450 2E1 (CYP2E1) responsible for alcohol breakdown in the case of chronic alcohol exposure commits the generation of ROS, resulting in fatty acids deposition and the progress of hepatic steatosis." (PMID 28070230, 2016). "Thus, phenobarbital-induced aggravation of fatty liver in HFD obese rats might have been induced, at least in part, by the exacerbation of NAFLD-related CYP2E1 induction." (PMID 28691103, 2017). "Although the mechanism whereby phenobarbital aggravated hepatic steatosis was not determined in this study, some data might suggest a role of CYP2E1 induction." (PMID 28691103, 2017).
Hepatic steatosis (continued). "Moreover, CYP2E1-null mice are protected against HFD-induced obesity and hepatic steatosis." (PMID 25887406, 2015). "It is not known whether different chain length fatty acids assist in the uncoupling of the CYP2E1 and CYP4A catalytic cycles or whether cytochrome b5, which increases P450 catalytic activity and prevents uncoupling, can reduce ROS formation in fatty liver disease." (PMID 20300478, 2009).
Obesity (66 papers, 2006 to 2026). Accumulation of substantial excess body fat. "Mechanistic studies suggest that obesity is associated with increased activity of cytochrome P450 2E1 (CYP2E1), an enzyme that metabolizes folate as a substrate." (PMID 40276534, 2025). "There is growing evidence that CYP2E1 plays a role in the progression of obesity-associated fatty liver to NASH." (PMID 35053404, 2022). "Lastly, CYP2E1 seems to favor the progression of obesity-associated fatty liver to NASH, which is characterized by necroinflammation and fibrosis." (PMID 35053404, 2022). "Diabetes and obesity are complex, interrelated conditions associated with increased CYP2E1 mRNA expression and/or activity in humans." (PMID 24647036, 2014). "Collectively, these findings identify CYP2E1 as a previously unrecognized regulator of obesity-associated metabolic dysfunction and establish Q11 as a promising therapeutic candidate that concurrently suppresses inflammation and reinstates mitochondrial homeostasis." (PMID 41420839, 2025). "Gout, obesity, and acute myeloid leukemia were some of the traits that were associated with CYP2E1." (PMID 39457450, 2024). "Further, an insertion polymorphism in the regulator region of the CYP2E1 gene increases the activity of CYP2E1 protein only under conditions of obesity, suggesting that both genotype and environment interact to increase risk for diseases associated with CYP2E1 activation." (PMID 39058136, 2024). "Studies have shown that the subjects with diabetes, obesity, or MetS, had an increased activity of CYP2E1, which might be associated with both hepatic toxin metabolism and the development of liver fibrosis." (PMID 35223941, 2022). "In contrast, alcohol intoxication in leptin-deficient obese mice increased CYP2E1 activity only in liver microsomes but not in mitochondria, thus suggesting that leptin deficiency and/or obesity might hamper mitochondrial targeting of induced CYP2E1." (PMID 35053404, 2022). "“CYP2E1 reactions” have previously been linked to obesity-induced oxidative stress." (PMID 34835991, 2021). "CYP2E1 expression has been reported to be inhibited by insulin, and to be associated with obesity." (PMID 31031804, 2019). "NASH phenotype was associated with liver fibrosis, obesity, hyperleptinemia, increased oxidative and ER stress, inflammation, and increased IR and impaired GT (multiple 2nd hits) in WT-fed FF compared to the corresponding Cyp2e1-null mice." (PMID 28051126, 2017). "As an antioxidant, capsaicin can inhibit free radicals induced by alcohol to alleviate the symptoms of hypertension, dyslipidemia, and obesity caused by oxidative stress, which may be related to the expression of cytochrome P450 2E1 (CYP2E1) and related receptors." (PMID 38612538, 2024). "Finally, it should be underlined that chronic ethanol consumption constantly causes hepatic CYP2E1 induction while recent investigations reported that alcohol consumption and obesity (or metabolic syndrome) can synergistically augment the risk and severity of steatohepatitis, cirrhosis and HCC." (PMID 36713231, 2023). "Moreover, there is increasing evidence that CYP2E1 plays a significant role in obesity-associated nonalcoholic fatty liver disease (NAFLD), in particular by favoring the progression of simple fatty liver (i.e., steatosis) to nonalcoholic steatohepatitis (NASH)." (PMID 35053404, 2022). "This work provides a mechanistic and translational foundation for targeting CYP2E1 in obesity and related metabolic disorders." (PMID 41420839, 2025). "When HIBD coexists with obesity, the combined metabolic burden leads to upregulation of hepatic cytochrome P450 2E1 (CYP2E1) activity and excessive ROS generation, exacerbating oxidative damage and liver dysfunction." (PMID 40777174, 2025).
Obesity (continued). "The regions showing association with obesity‐related phenotypes are located at 11q11 (OR4P4, OR4S2, OR4C6), 1p21.1 (AMΥ1), 10q11.22 (NPY4R), 10q26.3 (CYP2E1), 16q12.2 (FTO), 16p12.3 (GPRC5b), and 4q25 and have been associated with adult obesity as well." (PMID 41082226, 2025). "Here, we evaluate the functional role of CYP2E1 in obesity and the therapeutic potential of a highly selective CYP2E1 inhibitor, 4-methyl-5-acetylthiazole (Q11)." (PMID 41420839, 2025). "Although cytochrome P450 2E1 (CYP2E1) is implicated in oxidative stress and inflammatory signaling, its contribution to adipocyte dysfunction during obesity remains insufficiently defined." (PMID 41420839, 2025). "For example, MACROD2, PHLPP2, CYP2E1, and STT3B are associated with obesity in the body, play a role in fat metabolism, and there is a close link between them and growth traits." (PMID 40244387, 2025). "Recent studies suggest that individuals with obesity have enhanced activity of the acrylamide-metabolizing P450 enzyme, CYP2E1, in the liver." (PMID 39058136, 2024). "Studies have shown that NAFLD patients have increased expression of CYP2E1, and hepatic CYP2E1 is often induced in obesity and related metabolic disorders." (PMID 39061900, 2024). "It is important to highlight that the percentage of conversion from acrylamide to glycidamide is influenced by the expression of liver CYP2E1, which is induced by alcohol consumption, drugs, physical development, hormonal status, obesity, and diabetes." (PMID 39770901, 2024). "It has been demonstrated that animals with diet-induced obesity express more hepatic CYP2E1 protein and better metabolize typical CYP2E1 substrates." (PMID 36670991, 2023). "Exogenous (e.g., ethanol, pyrazole, isoniazid) or endogenous (e.g., obesity, diabetes, fasting, hypophysectomy) factors can both increase CYP2E1 activity." (PMID 36670991, 2023). "Hepatic CYP2E1 induction has also been found in many studies performed in different rodent models of obesity and NAFLD, although there are some exceptions as mentioned in Section 4.2.2." (PMID 36713231, 2023). "CYP2E1 has been related to metabolic diseases; its activity has been shown to be increased in patients with T2DM and obesity and several polymorphisms have been significantly associated with the risk of T2DM." (PMID 37834223, 2023). "Mitochondria and mitochondrial components such as DNA are particularly vulnerable to CYP2E1 induced oxidative stress, and that have been reported in multiple pathophysiological conditions, including obesity, diabetes and non-alcoholic steatohepatitis." (PMID 36494682, 2022). "This suggests a potential increase in CYP2E1 activity and/or expression in children with obesity that drove two-fold higher absolute clearance." (PMID 35359853, 2022). "In animal models of NAFLD, LA reduced obesity and lipid accumulation in the liver, suppressed the expression of CYP2E1 and H2O2 production, and restored the lowered activity of antioxidant enzymes." (PMID 34200615, 2021). "In patients with obesity, an increase in cytochrome P450 2E1 (CYP2E1) activity and phase II conjugation activity has been observed." (PMID 34575306, 2021). "CYP2E1 gene transcription is induced or inhibited by numerous factors, such as liver function, fasting, obesity, alcohol intake, medication and various dietary factors." (PMID 33794901, 2021). "In obese rats, CYP2E1 was induced by overfeeding indicating a functional link between enzyme expression and obesity." (PMID 31349725, 2019). "Numerous studies carried out in rodents and humans have reported higher hepatic CYP2E1 expression and/or activity in obesity and NAFLD." (PMID 28691103, 2017). "Although different clinical investigations consistently showed that liver CYP2E1 activity is statistically greater in obesity and NAFLD, this activity is highly variable in obese patients." (PMID 28691103, 2017).
Obesity (continued). "Unfortunately, unlike the painkiller APAP, no investigations have been carried out in experimental NAFLD models in order to confirm that higher hepatic CYP2E1 activity is responsible for increased halothane hepatotoxicity in obesity." (PMID 28691103, 2017). "We propose that BI-1 protects against obesity-induced hepatic insulin resistance by regulating CYP2E1 activity and ROS production." (PMID 27576594, 2016). "In adults, CYP2E1 expression is influenced by age, obesity, diabetes and other chronic diseases, fasting, diet, and exposure to CYP2E1 inducers (e.g., ethanol, benzene, acetone) and substrates (e.g., caffeine, acetaminophen)." (PMID 24647036, 2014). "Its activity results in the production of reactive oxygen species and CYP2E1 KO mice are protected against diet induced obesity." (PMID 24842286, 2014). "Obesity, age, and smoking, as well as consumption of alcohol and certain drugs, have been shown to modulate CYP2E1 expression." (PMID 16581535, 2006). "Furthermore, CYP2E1 interacts with the nuclear receptor PPARα to co-regulate obesity, and CYP2E1 gene knockout mice show significantly improved obesity and dyslipidemia under high-fat diets." (PMID 39859169, 2025). "It has been shown that CYP2E1 activity is higher in patients suffering from obesity due to MetS." (PMID 40662170, 2025). "In addition, several genes were identified that are associated with obesity and play roles in lipid metabolism, including MACROD2, PHLPP2, CYP2E1, and STT3B." (PMID 40244387, 2025). "Increased obesity through the Western diet may further fuel DNA damage through elevated expression of CYP2E1 to metabolize acrylamide to genotoxic intermediates." (PMID 39058136, 2024). "Consistent with studies focused on patients with obesity, obese mice had elevated levels of CYP2E1." (PMID 39058136, 2024). "Indeed, increased CYP2E1 protein expression and activity have been found in obesity, alcoholic liver disease (ALD), and NAFLD in both humans and rodents." (PMID 37633951, 2023). "According to our results, the high-fat-fed control group had significantly higher CYP2E1 expression compared to group I. This group had significant weight gain, so it is all in accordance with other studies showing that high-fat diets and obesity lead to CYP2E1 overexpression." (PMID 38004588, 2023). "As discussed in this review, obesity, NAFLD and both types 1 and 2 diabetes could also predispose to APAP liver injury, at least in part, due to higher hepatic CYP2E1 activity." (PMID 36713231, 2023). "Although this might suggest that the leptin signaling pathway is needed for CYP2E1 induction in obesity and NAFLD, hepatic CYP2E1 activity is enhanced in leptin receptor-deficient db/db mice, especially in females." (PMID 36713231, 2023). "Hepatic CYP2E1 induction is a salient feature of obesity and NAFLD." (PMID 36713231, 2023). "In our study, CYP2E1 expression in the liver rose in Group II compared to Group I. This finding corroborates other studies, saying that CYP2E1 was increased in obesity, fatty liver, NAFLD, and NASH in both humans and rodents, and this increase appears to correlate well with the severity of NAFLD." (PMID 38004588, 2023). "Moreover, it has been reported that the CYP2E1 is an oxidative stress-related gene in several pathophysiological conditions including obesity, diabetes, and metabolism." (PMID 36494682, 2022). "Moreover, spermatogenesis disorders and the overexpression of CYP2E1 mRNA have been correlated in male rats with experimental alcoholism, type I diabetes, and obesity." (PMID 35739948, 2022). "Our results showed that higher methylation in cg20707527 (ZFPM2 gene) and lower methylation in cg11445109 (CYP2E1 gene) could have a role in the stability of the healthy phenotype in obesity." (PMID 34638758, 2021). "Additionally, CYP2E1 activity has been shown to be higher in patients with obesity and an animal model of metabolic syndrome." (PMID 34638758, 2021).